Y_RNA (Y RNA )
Gene: Miscellaneous RNA gene on chromosome 14 (28,901,236 to 28,901,347, reverse strand). Ensembl gene ENSG00000207164.
Homologues: Orthologues: chimpanzee Y_RNA (100% identical), macaque Y_RNA (93% identical). Paralogues in human: Y_RNA (85% identical), RNY1P5 (84% identical), Y_RNA (84% identical), Y_RNA (82% identical), Y_RNA (81% identical), Y_RNA (80% identical), RNY1P1 (79% identical), Y_RNA (79% identical), Y_RNA (78% identical), Y_RNA (77% identical), RNY1 (76% identical), Y_RNA (76% identical), and 94 more.